PPP1R14D (protein phosphatase 1 regulatory inhibitor subunit 14D)
Description:
Inhibitor of PPP1CA. Has inhibitory activity only when phosphorylated, creating a molecular switch for regulating the phosphorylation status of PPP1CA substrates and smooth muscle contraction.
Synonyms: GBPI-1; CPI17-like; FLJ20251; MGC119014; MGC119016; GBPI1
Tractability: No criterion of Open Targets' tractability assessment is met for any kind of drug.
Gene: Protein-coding gene on chromosome 15 (40,815,446 to 40,829,391, reverse strand). Ensembl gene ENSG00000166143.
Subcellular location: Cytoplasm
Gene Ontology:
Molecular function: protein serine/threonine phosphatase inhibitor activity
Cellular component: cytoplasm
Genetic constraint (gnomAD): Loss-of-function variants: 14 observed, 18.22 expected, observed/expected ratio (o/e) 0.77, 90% interval 0.51 to 1.2. The upper end of that interval is the gene's LOEUF score, 1.2, which puts it in group 5 of 6, group 1 being the genes least tolerant of losing a copy. Missense variants: 173 observed, 187.24 expected, observed/expected ratio (o/e) 0.92, 90% interval 0.82 to 1.05. Synonymous variants: 67 observed, 69.84 expected, observed/expected ratio (o/e) 0.96, 90% interval 0.79 to 1.18.
Homologues: Orthologues: dog PPP1R14D (89% identical), mouse Ppp1r14d (82% identical), guinea pig PPP1R14D (80% identical), rat Ppp1r14d (80% identical), rabbit PPP1R14D (79% identical), chimpanzee PPP1R14D (69% identical), macaque PPP1R14D (68% identical), tropical clawed frog ppp1r14d (30% identical), zebrafish ppp1r14d (29% identical), Caenorhabditis elegans F55C10.5 (20% identical), Drosophila melanogaster CG17124 (20% identical). Paralogues in human: PPP1R14C (32% identical), PPP1R14B (30% identical), PPP1R14A (27% identical).
Diseases named in the same sentence as PPP1R14D in open-access papers:
PPP1R14D is named in the same sentence as 6 diseases in open-access papers, as found by Europe PMC text mining. Sharing a sentence is not in itself a finding about the gene and the disease. The quoted sentences say what the papers report.
colon cancer (1 paper, 2021). "This included PPP1R14D, BST2 and ZNF550, whose expression was induced by 5-aza-2′-deoxycytidine (decitabine) treatment in colon cancer cell lines with low basal expression and high promoter methylation of these genes." (PMID 33892786, 2021).
diabetes (1 paper, 2021). "PPP1R14D (protein phosphatase 1 regulatory subunit 14D) is a metabolic signaling protein that is correlated with diabetes, and diabetes is a risk factor for PC." (PMID 34732125, 2021).
Hypertension (1 paper, 2025). The presence of chronic increased pressure in the systemic arterial system. "Among tissues linked to hypertension, PPP1R14D (Z = 3.12) and AMN (Z = 2.12) show maximal expression in kidney cortex, while PTMAP9 (Z = 1.16), RRAGA (Z = 1.37) and CREB1 (Z = 1.21) are most abundant in the aorta." (PMID 40909129, 2025).
tumor (2 papers, 2023 to 2025). "The relationship between methylation and expression of genes GSK3B, THBS1, and PTPN1 manifested a positive correlation in most tumour types, whereas this was reversed for genes PPP1R14D." (PMID 37815881, 2023).
PPP1R14D also shares sentences with these, for which no sentence is quoted: bladder cancer (1 paper); cancer (1).